SOX6 (SRY-box transcription factor 6)
Diseases named in the same sentence as SOX6 in open-access papers (continued):
Sharing a sentence is not in itself a finding about the gene and the disease.
endometriosis (1 paper, 2020). The growth of functional endometrial tissue in anatomic sites outside the uterine body. "miR-202, for example, was found to promote endometriosis by inhibiting SOX6, and downregulation of miR-375 alleviated the suppression of endothelin 1 (EDN1) in ectopic stromal cells, which in turn contributed to the development of endometriosis." (PMID 32112646, 2020).
Epileptic encephalopathy (1 paper, 2014). A condition in which epileptiform abnormalities are believed to contribute to the progressive disturbance in cerebral function. "As a consequence, the specific removal of Sox6 from this population results in a severe epileptic encephalopathy." (PMID 24662752, 2014). "Sox6 is shown to be important for normal positioning and maturation of MGE-derived interneurons, and that the specific deletion of Sox6 results in epileptic encephalopathy." (PMID 24662752, 2014).
generalized dystonia (1 paper, 2017). "Ebrahimi-Fakhari and colleagues reported a patient with generalized dystonia who was found to harbor a de novo heterozygous deletion in SOX6, another member of the SOXD subgroup." (PMID 29214085, 2017).
growth disorders (1 paper, 2021). "Interestingly, multiple sox family members (sox5, sox6, sox8, and sox18) were significantly dysregulated in shox-deficient pectoral fins together with other genes (nppa, nppc, cdkn1a, cdkn1ca, cyp26b1, and cy26c1), highlighting an important role for these genes in shox-related growth disorders." (PMID 34122528, 2021).
kidney neoplasm (1 paper, 2022). A benign or malignant neoplasm affecting the kidney. "The interaction between TYROBP, SOX6, and kidney neoplasms was drawn, and the inference score of TYROBP and SOX6 on the kidney neoplasms was high." (PMID 36595751, 2022).
mesothelioma (1 paper, 2024). A usually malignant and aggressive neoplasm of the mesothelium which is often associated with exposure to asbestos. "This is consistent with the previous detection of SOX6 in mesothelioma cells in the pleura, peritoneum and tunica vaginalis." (PMID 38212075, 2024).
metastatic disease (1 paper, 2018). "In the present study, we showed that Sox6 was down‐regulated in patients with PC and associated with metastatic disease." (PMID 29369542, 2018). "We showed that Sox6 is down‐regulated in patients with PC in association with metastatic disease." (PMID 29369542, 2018). "In addition, we found that Sox6 was down‐regulated in patients with metastasis than in those with non‐metastatic disease." (PMID 29369542, 2018).
non-small cell lung carcinoma (1 paper, 2019). A group of at least three distinct histological types of lung cancer, including non-small cell squamous cell carcinoma, adenocarcinoma, and large cell carcinoma. "For instance, miR-1269a acts as an onco-miRNA in non-small cell lung cancer (NSCLC) and promotes cancer cell growth by downregulating the expression of SOX6." (PMID 31164163, 2019).
Osteochondroma (1 paper, 2024). A common, benign cartiliginous neoplasm arising from the metaphysis of bone. "Recent studies have revealed that SOX6 variants can cause neurological syndromes related to hyperactivity disorder, cranial osteoporosis, and osteochondroma." (PMID 38205152, 2024).
scoliosis (1 paper, 2015). A congenital or acquired spinal deformity characterized by lateral curvature of the spine. "The mutant fish also exhibited a marked scoliosis; while this may be a secondary consequence of the defects in the skeletal muscle, it could also reflect a direct requirement for Sox6 in the vertebral column." (PMID 25671076, 2015). "Further analysis is required to determine whether the scoliosis in sox6 mutant fish is a reflection of such a requirement." (PMID 25671076, 2015).
Skeletal myopathy (1 paper, 2021). "Mice with a chromosomal inversion (p100H) disrupting the Sox6 gene, or carrying a targeted inactivation of Sox6 die perinatally, secondary to cardiac or skeletal myopathy." (PMID 33869190, 2021).
staphylococcus aureus infection (1 paper, 2022). An infectious process in which the bacteria Staphylococcus aureus is present. "In the aspect of KEGG, the genes related to TYROBP and SOX6 are mainly enriched in the staphylococcus aureus infection, phagosome, and cell adhesion molecules." (PMID 36595751, 2022).
Stroke (1 paper, 2012). Sudden impairment of blood flow to a part of the brain due to occlusion or rupture of an artery to the brain. "A possible future strategy might be to check the levels of some SOX6 and HES5 regulators such as miR-219 or miR-338 and their therapeutic potential in stroke." (PMID 23284893, 2012).
thalassemia (1 paper, 2010). An inherited blood disorder characterized by a decreased synthesis of one of the polypeptide chains that form hemoglobin. "We tested this possibility because imbalanced production of globin chains in thalassemia results in impaired maturation and survival of erythroid cells in a manner resembling the Sox6-null phenotype." (PMID 20711497, 2010).
Tolchin-Le Caignec syndrome (1 paper, 2022). "Moreover, SOX5 and SOX6 heterozygous inactivating variants cause poorly studied neurodevelopmental diseases in humans (Lamb-Shaffer and Tolchin-Le Caignec syndromes, respectively; OMIM: 616803 and OMIM: 618971)." (PMID 35108528, 2022). "Moreover, given the fact that SOX5 and SOX6 heterozygous inactivating variants cause neurodevelopmental diseases in humans (Lamb-Shaffer and Tolchin-Le Caignec syndromes, respectively), our findings will also shed light on the neural alterations present in those SOXopathies." (PMID 35108528, 2022).
vascular occlusion (1 paper, 2022). "This is the first study showing that the low expression of genes associated with epigenetic regulation, such as SOX6 and RBM33, may be related to vascular occlusion in MMD, whereas the overexpression of KCNMA1 and GALNT2 may be related to the vascular hyperplasia." (PMID 35368875, 2022).
tumor (57 papers, 2014 to 2026). "Lamina propria, SOX6, inflammation and tumor-associated fibroblasts were upregulated, while RSPO3 + fibroblasts were downregulated, and myofibroblasts maintained the same level as control samples." (PMID 38297356, 2024). "In addition, the cancer stemness score (RNAss) was negatively correlated with LAIR1 and VAMP8 and positively correlated with CKAP2L and SOX6, indicating that these hub genes are linked to tumor stemness-related characteristics." (PMID 41614933, 2026). "Furthermore, the SOX6 level in HCC tissues is relatively low, and the SOX6 expression is negatively associated with the tumor stage and the serum AFP level." (PMID 35267473, 2022). "SRY-box transcription factor 6 (SOX6) levels are inversely correlated with metastasis in cancer, and CDKN1A and CCND1 are upregulated and downregulated, respectively, by SOX6, suggesting that its tumor-suppressive function is associated with cell cycle regulation." (PMID 33435156, 2021). "Thus, it is tempting to speculate that the observed inter-tumor heterogeneity in SOX6 expression of EwS tumors and EwS cell lines is likely caused by inter-individual differences in the number of consecutive GGAA-repeats at this SOX6-associated GGAA-mSat." (PMID 32415069, 2020). "Further in vivo validation using a tail vein injection model with SOX6_OE A375 cells in nude mice confirmed that SOX6 overexpression drives tumor progression and metastatic dissemination." (PMID 40866912, 2025). "To verify the role of SOX6 expression in promoting tumor invasion in AM, we established SOX6-overexpressing (SOX6_OE) A375 and SK-MEL-28 stable cell line via lentivirus transduction and checked the cell proliferation and invasive capabilities." (PMID 40866912, 2025). "The pro-invasive role of overexpressed SOX6 was validated in vivo and in vitro, including its ability to enhance tumor invasion by upregulating cellular glycolysis, disrupt fatty acid transport, and increase intracellular phosphatidylcholine content." (PMID 40866912, 2025). "We propose that SOX6 + tumor-promoting effects in AM originate from its ability to rewire lipid metabolism - a mechanism repurposed from its physiological functions - thereby highlighting its potential as a therapeutic target for cancer treatment in AM." (PMID 40866912, 2025). "SOX6 were reported to play dual functional roles in oncogenesis, acting as either a tumor suppressor or oncogene depending on specific cancer types and cellular contexts." (PMID 40866912, 2025). "Overall, our data reveal a mechanism by which SOX6 can act as a tumor suppressor in LIN28B-positive cancer cells." (PMID 38704454, 2024). "Molecular studies revealed that the inhibitory effect of PACAP38 on tumor cell proliferation was mediated by upregulating SOX6 protein expression through histone acetylation, thereby inhibiting the Wnt-β-catenin signaling pathway." (PMID 39619607, 2024). "Previous studies have suggested the potential involvement of Sox6 in the EMT of numerous tumor cells, engaging various downstream pathways/factors, including Twist1, the Akt pathway, and the Wnt/β-catenin pathway." (PMID 38294713, 2024). "Multiple studies have demonstrated that SOX6 exerts its tumor-suppressive role by downregulating the Wnt/β-catenin signaling pathway, which plays a pivotal role in the initiation and progression of various cancers." (PMID 39619607, 2024). "Based on our observations, we propose a general model in which SOX6 acts as a tumor suppressor in cells of different tissue origin acting through the LIN28B/Let-7 pathway." (PMID 38704454, 2024). "We further explored the tumor suppression mechanisms operating downstream of the PACAP38/SOX6 axis in cancer cells." (PMID 39619607, 2024). "We demonstrated statistically significant differences in expression between normal and primary tumor tissues for SOX6, SOX8, SOX21 and SOX30 genes and pointed to SOX6 as the one that met the independent diagnostic markers criteria." (PMID 38132438, 2023).
tumor (continued). "SOX6 can also be involved in tumorigenesis as an oncogene or tumor suppressor in different types of cancer." (PMID 38132438, 2023). "SOX-6, known for its tumor suppressive properties across multiple malignancies, exhibits the ability to inhibit tumor development." (PMID 38124072, 2023). "According to the proposed chronology, the C1 SOX6+ Oligodendrocytes subpopulation corresponds to the early stages of tumor development and continues to differentiate into other subpopulations." (PMID 38274814, 2023). "Inhibition of SOX6 effectively countered the inhibitory roles effects on tumor migration, invasion and drug resistance of MM cells mediated by the inhibition of miR-182 in BMSCs-Exos." (PMID 38062424, 2023). "SOX6 has previously been shown to function as a tumor suppressor, limiting cell proliferation; in support, we identified expression of Sox6 within the sutural mesenchyme and progenitor cell populations surrounding the suture." (PMID 36980886, 2023). "For example, SOX6 suppressed tumor invasion by mediating the transcription of twist, a transcription factor involved in the promotion of EMT." (PMID 33797657, 2022). "Growing evidence has demonstrated that SOX6 serve as a tumor suppressor in the onset and progression of human cancer." (PMID 34868396, 2021). "In this model, miR-499a-5p was shown to target SRY-Box Transcription Factor 6 (SOX6) an important tumor suppressor playing roles in cell proliferation, differentiation, and cell fate determination." (PMID 33803151, 2021). "To assess the potential contribution of SOX6 to EwS tumor growth in vivo, we performed xenograft experiments by injecting two different EwS cell lines with Dox-inducible shRNAs against SOX6 or control shRNA subcutaneously into the flanks of NSG mice." (PMID 32415069, 2020). "Here, the authors show that EWSR1-FLI1 increases the activity of the developmental transcription factor SOX6, which promotes tumor growth but also increases sensitivity to oxidative stress." (PMID 32415069, 2020). "Both analyses showed that SOX6 is highly expressed in EwS tumors, albeit with substantial inter-tumor heterogeneity." (PMID 32415069, 2020). "In synopsis, we discovered that EWSR1-FLI1 hijacks SOX6 in EwS, which promotes tumor growth and modulates intracellular oxidative stress levels creating a therapeutic vulnerability toward oxidative stress-inducing drugs." (PMID 32415069, 2020). "To identify the mechanism through which SOX6 inhibits tumor growth, we next analyzed the cell cycle." (PMID 31729835, 2020). "Future studies should further explore the role of Sox6 in the regulation of tumour cell proliferation mediated by the modulation of chromatin structure via histone modifications." (PMID 29369542, 2018). "In vivo experiments showed that Sox6 overexpression inhibited tumour growth and liver metastasis from PC, confirming that Sox6 plays a tumour suppressor role in PC." (PMID 29369542, 2018). "IHC assay showed that PCNA was down‐regulated in the tumour tissues developed from Sox6 overexpressing PC cells, which was a marker for cell proliferation." (PMID 29369542, 2018). "In a mouse model of PC, mice injected with Sox6 overexpressing PC cells developed smaller tumours than those receiving control vector‐transfected cells." (PMID 29369542, 2018). "Sox6 overexpression suppressed PC cell proliferation and migration in vitro and tumour growth and liver metastasis in vivo." (PMID 29369542, 2018). "rs73239138 in miR-1269a has been identified as a protective factor which prevents binding to 3’UTR of SOX6 and there by suppresses tumor growth in HCC." (PMID 29467929, 2018).
tumor (continued). "Twist1 overexpression reversed the effect of Sox6 on inhibiting EMT, confirming that the effect of Sox6 on suppressing tumour invasiveness is mediated by the modulation of Twist1 expression." (PMID 29369542, 2018). "The mRNA and protein expressions of Sox6 were analysed in tumour and adjacent peritumour tissues from patients with PC." (PMID 29369542, 2018). "The results of qPCR analysis showed that Sox6 expression was lower in tumour than in peritumour tissues." (PMID 29369542, 2018). "When investigating the SKCM dataset, we found SOX9, SOX2 as well as SOX6 to be down-regulated in the tumor subgroup of low SOX5 expression compared to the tumor subgroup of high SOX5 expression." (PMID 26927636, 2016). "A previous study showed that SOX6 is a tumor-suppressor and plays an important role in ESCC progression." (PMID 25023649, 2014). "SNP rs73239138 in miR‐1269 affects binding to SOX6, suppressing tumor growth in HCC." (PMID 41409896, 2025). "SOX6 were demonstrated to enhance cell invasiveness by elevating glycolysis, and regulating tumor fatty acid transport to increase intracellular PC and PE content, thereby affecting the tumor microenvironment." (PMID 40866912, 2025). "Additionally, the reduced proliferative capacity of tumor cells following SOX6 overexpression further validates its tumor-suppressive function." (PMID 39619607, 2024). "Moreover, NTN1 overexpression significantly inhibited the expression of SOX6, reversing the effects of SOX6 on cell proliferation and invasion in vitro and tumour xenograft growth and vascularity in vivo." (PMID 38546656, 2024). "SOX6 could significantly reduce the volume, size, and weight of xenograft tumor in mice, depending on its HMG domain." (PMID 38383842, 2024). "However, there is no research investigating the relationship between SOX6 and p21 in AF, and only several studies have unraveled that SOX6 can suppress tumor cell proliferation via upregulation of p21 and augment cell senescence." (PMID 37197357, 2023). "The SOXD group of potential tumor suppressors in GBM comprises SOX5, SOX6, and SOX13." (PMID 37047365, 2023). "In non-small cell lung cancer, miR-1269a can down-regulate SOX6 to promote tumor growth." (PMID 35252180, 2022). "SOX6 reduces tumor cell proliferation by promoting the expression of P21 and inhibiting CyClin D1." (PMID 35252180, 2022). "Next, we showed the expression of SOX6 and FBXO2 was also positively correlated in some tumor types in the TCGA database, including OV, suggesting that SOX6 may be involved in the regulation of FBXO2 expression in OV." (PMID 35525855, 2022). "SOX6 functions as a tumor suppressor and mediates various miRNAs to affect HCC progression." (PMID 35267473, 2022). "The results were consistent with what was reported in the literature, indicating that SOX6 may serve as a tumor suppressor, while SOX12 may serve as an oncogene in ccRCC." (PMID 34868396, 2021). "Moreover, 16 of the top 20 CIS genes had supporting fusion transcripts from at least one tumor, including Cdkn2a, Nf1, Pten, Sox6, Sox5, Spred1, and Tcf12 (all containing PB splice acceptor fusions, implying transcript termination)." (PMID 32727536, 2020). "Taken together, these results indicated that Sox6 plays a tumour suppressor role in PC." (PMID 29369542, 2018). "The down‐regulation of Sox6 expression by microRNA‐208 in relation to increased cell proliferation and tumorigenicity in oesophageal squamous cell carcinoma supports the tumour suppressor role of Sox6 29, which is consistent with the findings of the present study." (PMID 29369542, 2018). "It is reported that Sox6 plays a tumor-suppressive role in cancers." (PMID 27895893, 2016). "SOX6 is reported to have a tumor-suppressive function in tumors." (PMID 25023649, 2014). "SOX6 has been reported to play a tumor-suppressive function in certain tumors." (PMID 25023649, 2014).